MAGI1 (membrane associated guanylate kinase, WW and PDZ domain containing 1)
Description:
Plays a role in coupling actin fibers to cell junctions in endothelial cells, via its interaction with AMOTL2 and CDH5 (By similarity). May regulate acid-induced ASIC3 currents by modulating its expression at the cell surface (By similarity).
Synonyms: AIP-3; BAP-1; MAGI-1; WWP3; AIP3; BAIAP1; BAP1; TNRC19; MAGI-1b; Magi1d
Tractability: Small molecule: a structure with a bound ligand is known; it has a high-quality binding pocket. Antibody: UniProt places it where antibodies can reach, with high confidence; its Gene Ontology location is reachable by antibodies, with high confidence. PROTAC: ubiquitination databases record sites on it; its protein half-life has been measured.
Gene: Protein-coding gene on chromosome 3 (65,353,525 to 66,038,918, reverse strand). Ensembl gene ENSG00000151276.
Subcellular location: Cell junction, tight junction; Cell membrane
Subcellular location (Human Protein Atlas): Cell Junctions; Nucleoplasm
Gene Ontology:
Molecular function: alpha-actinin binding; protein binding
Biological process: positive regulation of cell-cell adhesion; cell adhesion; cell surface receptor signaling pathway; endothelial cell morphogenesis; protein-containing complex assembly; signal transduction
Cellular component: cell junction; cell periphery; cell projection; cell-cell junction; cytoplasm; plasma membrane; adherens junction; bicellular tight junction; membrane
Genetic constraint (gnomAD): Loss-of-function variants: 51 observed, 130.44 expected, observed/expected ratio (o/e) 0.39, 90% interval 0.31 to 0.49. The upper end of that interval is the gene's LOEUF score, 0.49, which puts it in group 2 of 6, group 1 being the genes least tolerant of losing a copy. Missense variants: 1,797 observed, 1,905.2 expected, observed/expected ratio (o/e) 0.94, 90% interval 0.91 to 0.98. Synonymous variants: 780 observed, 753.37 expected, observed/expected ratio (o/e) 1.04, 90% interval 0.98 to 1.1.
Homologues: Orthologues: chimpanzee MAGI1 (99% identical), macaque MAGI1 (99% identical), pig MAGI1 (95% identical), rat Magi1 (94% identical), dog MAGI1 (88% identical), rabbit MAGI1 (86% identical), mouse Magi1 (80% identical), tropical clawed frog magi1 (79% identical), guinea pig MAGI1 (70% identical), zebrafish magi1b (63% identical), zebrafish magi1a (50% identical). Paralogues in human: MAGI2 (44% identical), MAGI3 (38% identical), GRIP1 (15% identical), GRIP2 (14% identical), SAV1 (7% identical), MAGIX (7% identical).
Diseases named in the same sentence as MAGI1 in open-access papers:
MAGI1 is named in the same sentence as 65 diseases in open-access papers, as found by Europe PMC text mining. Sharing a sentence is not in itself a finding about the gene and the disease. The quoted sentences say what the papers report.
breast cancer (7 papers, 2016 to 2023). A primary or metastatic malignant neoplasm involving the breast. "MAGI1 acts as a tumor suppressor in estrogen receptor-positive (ER+) breast cancer (BC), and its loss correlates with a more aggressive phenotype." (PMID 37566008, 2023). "The results showed that MAGI1 mutations or copy number alterations (CNA) are rare as they are observed in less than 3% of all breast cancers, and 2% within ER+/HER2− BC, indicating that DNA alterations are not the major cause of MAGI1 downregulation." (PMID 31963297, 2020). "Recently, MAGI1 was reported to be expressed at higher levels in estrogen receptor (ER)+/HER2- breast cancers (BCs), relative to HER2+ and triple negative (TN) BCs." (PMID 34198584, 2021). "On the one hand, MAGI1 silencing in the MCF7 breast cancer cell line decreases ESR1 mRNA and ERα protein levels, activates PI3K/Wnt signaling, promotes cell proliferation, and reduces apoptosis and epithelial differentiation." (PMID 34503076, 2021). "In luminal breast cancer MCF7 cell line, downregulation of MAGI1 is associated with an increased accumulation of AMOTL2 (Angiomotin Like 2) and of E-cadherin, and to enhanced cell proliferation, but not cell migration or invasiveness." (PMID 34503076, 2021). "In estrogen receptor-positive (ER+)/human epidermal growth factor receptor 2 negatives (HER2−) breast cancers, MAGI1 is considered a tumor suppressor." (PMID 34503076, 2021). "Taken together, we show that MAGI1 is a new potential tumor suppressor in ER+/HER2− breast cancer with possible prognostic value for the identification of patients at high-risk of relapse within this subset." (PMID 31963297, 2020). "In order to corroborate this observation with clinical evidence, we performed HE, ER, and MAGI1 IHC staining of human breast cancer tissues." (PMID 31963297, 2020). "Here we report, based on experimental results and human breast cancer (BC) patients’ gene expression data, that MAGI1 is highly expressed and acts as tumor suppressor in estrogen receptor (ER)+/HER2− but not in HER2+ or triple negative breast cancer (TNBC)." (PMID 31963297, 2020). "To address this question, we analyzed METABRIC and TCGA gene expression data sets of primary human breast cancers and observed that MAGI1 expression is higher in ER+/HER2− compared to HER2+ and ER−/HER2− BC subtypes." (PMID 31963297, 2020). "Within promoter regions, the top DEGs upregulated in EA was MAGI1, a junctional scaffold protein that acts as a tumor suppressor in the context breast cancer through inhibition of the p38 stress pathway, and SMG6, which has been implicated in DNA repair and telomere maintenance." (PMID 37732899, 2023). "Stimulated by these observations we sought to analyze whether MAGI1 may also act as a tumor suppressor in breast cancer." (PMID 31963297, 2020). "The premature polyadenylation of MAGI1 and MAGI3 transcripts have been evidenced in human small intestinal neuroendocrine tumors and breast cancers, respectively." (PMID 34503076, 2021). "Among these, 34 hotspot mutations such as CD209 R129 missense (4.0 %) in bladder cancer, MAGI1 Q421 insertion (0.8 %) and NR1H2 Q175 insertion (1.8 %) in breast cancer were not well investigated based on previous studies and are potentially novel targets." (PMID 27356755, 2016).
cervical cancer (7 papers, 2011 to 2024). A primary or metastatic malignant neoplasm involving the cervix. "The loss of TJ integrity is a direct consequence of the loss of MAGI-1 in cervical cancer cell lines HeLa and CaSKi, which is reinstated upon E6 ablation and the re-emergence of MAGI-1 expression in these cells." (PMID 26147797, 2015). "Membrane-associated guanylate kinase inverted 1 (MAGI1), as a member of the membrane-associated guanylate kinase family, was downregulated in diverse cancers and was a tumor suppressor in colorectal cancer, hepatocellular carcinoma, cervical cancer and gastric cancer in previous reports." (PMID 31228945, 2019). "Our results are consistent with previous results from human cervical cancer cells in which MAGI-1, hDlg-1 and hScrib are targeted for degradation by E6." (PMID 27537218, 2016). "Deletion of this motif in HPV16 E6 impaired its capacity to promote cancer in transgenic mice indicating that binding of E6 to MAGI1 and SCRIB might be implicated in the development of cervical cancer." (PMID 22069443, 2011). "Indeed, levels of both proteins are rescued upon silencing E6 expression in HPV-positive cervical cancer cell lines, although the most marked change was noted for MAGI-1, with membrane bound and nuclear pools of the protein restored and re-localization of MAGI-1 to tight junctions." (PMID 26797638, 2016). "For instance, the oncoprotein E6 produced by the human papillomaviruses (HPV) responsible for cervical cancer contains a PDZ-binding motif, which interacts with PDZ domains of MAGI1 and SCRIB." (PMID 22069443, 2011).
gastric cancer (7 papers, 2014 to 2023). A primary or metastatic malignant neoplasm involving the stomach. "MAGI1 expression is decreased in some inflammatory diseases and in several cancers, including hepatocellular carcinoma, colorectal, cervical, brain, and gastric cancers." (PMID 37566008, 2023). "In a panel of different gastric cancer cell lines, MAGI1 knockdown significantly enhanced migration and invasion of these cells by altering the expression of MMPs and EMT-related molecules via inhibiting the MAPK/ERK signaling pathway." (PMID 34198584, 2021). "MAGI1 acts as tumor suppressors in a multitude of cancers, in particular liver, colorectal, cervical, breast, brain, and gastric cancers, serving in some cases as a prognostic marker." (PMID 34198584, 2021). "MAGI1 expression was shown to be downregulated in several cancers, including hepatocellular carcinoma, colorectal, cervical, and gastric cancers, but little is known about its expression in BC and its subtypes." (PMID 31963297, 2020). "The expression of MAGI1, a cytoplasmic scaffolding protein, is decreased in some inflammatory diseases and in several cancers, including hepatocellular carcinoma and colorectal, cervical, breast, brain, and gastric cancers." (PMID 36308410, 2022). "MAGI1 expression is downregulated during cancer progression and was proposed to act as a tumor suppressor in several cancers, including hepatocellular carcinoma, colorectal, cervical and gastric cancers." (PMID 31963297, 2020). "Furthermore, previous studies have shown that downregulation of MAGI1 is associated with poor prognosis of HCC and that overexpression of CUL1 is associated with poor prognosis of patients with gastric cancer." (PMID 24988079, 2014). "In the TCGA cohort, gastric cancer (GC) harboring variants in RECQL4, ARID1A, MAGI1, or JAK3 were 4.5% (n = 20), 27.0% (n = 119), 7.5% (n = 33), or 3.8% (n = 17), respectively." (PMID 33328548, 2020).
colorectal cancer (5 papers, 2019 to 2023). A primary or metastatic malignant neoplasm that affects the colon or rectum. "Previous studies on MAGI1 have shown that its downregulation in ER+HER2− BC cells generates a more aggressive phenotype and that silencing MAGI1 in colorectal cancer cells accelerates primary tumor growth and promotes metastasis." (PMID 37566008, 2023). "We have previously shown that in colorectal cancer, MAGI1 expression is negatively or positively regulated by PGE2 or COX-2 inhibitors (COXIBs), respectively." (PMID 31963297, 2020). "We have previously shown that silencing MAGI1 expression in colorectal cancer (CRC) cells promotes primary tumor growth and metastasis associated with loss of E-cadherin at cell contacts and Wnt signaling activation, while MAGI1 overexpression had opposite effects." (PMID 31963297, 2020). "Intriguingly, in breast and colorectal cancers, MAGI1 expression is induced by non-steroidal anti-inflammatory drugs (NSAIDs), suggesting a role in mediating the tumor suppressive activity of NSAIDs." (PMID 34198584, 2021).
schizophrenia (5 papers, 2010 to 2025). A major psychotic disorder characterized by abnormalities in the perception or expression of reality. "As already mentioned, MAGI1 copy number variations were found associated with bipolar affective disorder and schizophrenia." (PMID 34198584, 2021). "Genome-wide association studies (GWAS) for the uncovering of polygenic association with depressive disorders found that MAGI1 copy number variations and polymorphism are associated with schizophrenia, bipolar disorders, and depressive episodes." (PMID 34198584, 2021). "The MAGI1 gene polymorphism was further validated in an independent sample of unrelated bipolar, schizophrenia and schizoaffective disorder cases, and thus, represents an interesting candidate for future studies." (PMID 26692414, 2015). "Several suppressors, such as magi-1, lin-12, and ina-1, have human orthologs implicated in the pathogenesis of schizophrenia but have not been previously shown to mediate the biological effects of an APD." (PMID 23468647, 2013).
Crohn disease (4 papers, 2017 to 2025). A gastrointestinal disorder characterized by chronic inflammation involving all layers of the intestinal wall, noncaseating granulomas affecting the intestinal wall and regional lymph nodes, and transmural fibrosis. "MAGI-1 is associated with Crohn's disease (CD) and microscopic colitis." (PMID 40625359, 2025). "A genome-wide association study revealed a strong association between MAGI1 locus and various chronic inflammatory diseases including Crohn's disease, in which MAGI1-dependent maintenance of the tight seal of the gastrointestinal tract is compromised." (PMID 36082118, 2022). "Allelic associations between TJ-related genes (F11R, MAGI1, MAGI2, MAGI3, PARD3, PTEN, and TJP1) and IBD, Crohn’s disease (CD), or ulcerative colitis (UC) were investigated." (PMID 28545409, 2017).
atherosclerosis (3 papers, 2019 to 2025). A disease characterized by the build-up of fatty material and calcium deposition in the arterial wall resulting in partial or complete occlusion of the arterial lumen. "MAGI1 is emerging as a protein exerting multiple, essential cellular functions and implicated in important human pathologies, particularly in cancer and atherosclerosis." (PMID 34198584, 2021). "While MAGI1 loss seems a common feature in many different cancers and inflammatory diseases, ECs activation and consequent MAGI1 upregulation contribute to the pathogenesis of atherosclerosis." (PMID 34198584, 2021). "In addition, due to its important role in regulating permeability, MAGI1 inhibition may cause increased EC permeability, which may enhance atherosclerosis formation." (PMID 34198584, 2021). "Considering the importance of NO metabolism in many cardiovascular diseases, in particular atherosclerosis and hypertension, it will be important to assess whether endothelial MAGI1 function or dysfunction may be involved in the genesis or progression of such pathologies." (PMID 31035633, 2019). "A plausible mechanistic model may involve TNIK interaction with MAGI1, a PDZ domain–containing scaffold protein previously shown to regulate ER stress signaling and atherosclerosis in ECs." (PMID 40672381, 2025).
colon cancer (3 papers, 2015 to 2021). "In this connection, celecoxib, a Cox-2 inhibitor upregulates MAGI1 in the human colon cancer SW480 and HCT116 cell lines, curtailing primary tumor growth and spontaneous lung metastasis in an orthotopic model of colorectal cancer." (PMID 34503076, 2021). "MAGI1 expression in colon cancer cells is downregulated by prostaglandin-E2 (PGE2), a main product of cyclooxgenase-2 (COX-2)." (PMID 26452219, 2015). "Recent research identified MAGI1 as a negative regulator of the Wnt/β-catenin signaling pathway, with tumor-suppressive and anti-metastatic activity in colon cancer." (PMID 26452219, 2015).
glioma (3 papers, 2021 to 2024). A benign or malignant brain and spinal cord tumor that arises from glial cells (astrocytes, oligodendrocytes, ependymal cells). "Next generation DNA sequencing studies performed in atypical choroid plexus papilloma, a rare benign tumor of the central nervous system that is usually confined to the cerebral ventricles, identified, along other genes, missense mutations in the MAGI1 gene." (PMID 34198584, 2021). "Via the Wnt/β-Catenin and PTEN/AKT signaling pathways, MAGI1 silencing inhibits apoptosis of glioma cells and promotes proliferation." (PMID 34422806, 2021). "MAGI1 is a favorable prognostic marker in renal cancer, while in HCC and glioma, low MAGI1 expression is associated with poor prognosis." (PMID 34198584, 2021). "Another study found that overexpressing MAGI1 inhibits proliferation, migration, and invasion of glioma cells by regulating cell growth and EMT through AKT, matrix metalloproteinase 2 (MMP2) and MMP9, and the E-cadherin/N-cadherin/vimentin pathway." (PMID 34198584, 2021). "Overexpression of MAGI1 can affect AKT, MMP2, and MMP9 and inhibit the invasion and migration of glioma cells." (PMID 39458959, 2024).
renal carcinoma (3 papers, 2020 to 2023). A carcinoma arising from the epithelium of the renal parenchyma or the renal pelvis. "MAGI1 has been reported to be a tumor suppressor gene in colorectal, gastric, and renal cancer, and knockdown of this gene has been shown to result in migration and invasion in vitro." (PMID 32183222, 2020). "Another study revealed that in renal cancer MYB activated the transcription of miR-520h, which targeted MAGI1 and down-regulated its expression to suppress invasiveness and metastasis of tumor." (PMID 36994664, 2023).
adenovirus infection (2 papers, 2010 to 2023). "Binding of CXADR with the PDZ-3 domain of MAGI suppresses apical CXADR protein expression and adenovirus infection, while expression of the MAGI-1 PDZ1 domain can rescue CXADR from MAGI-1-mediated suppression and facilitate adenovirus infection." (PMID 36674801, 2023).
bipolar affective disorder (2 papers, 2015 to 2021). "Previous studies have demonstrated an association of MAGI1 copy number variation with bipolar affective disorder." (PMID 26075115, 2015).
diabetes (2 papers, 2021 to 2026). "This study not only delineates a previously unrecognized mechanism but also identifies the OGT/MAGI1 axis as a potential therapeutic target for preventing vascular complications in diabetes." (PMID 41546072, 2026).
ocular sarcoidosis (2 papers, 2021 to 2024). A leading cause of inflammatory eye disease is sarcoidosis. "While the HLA-DRB1*0401 and MAGI1 genes represent susceptibility to ocular sarcoidosis." (PMID 39598118, 2024).
renal cell carcinoma (2 papers, 2021). "Regarding MAGI1, a recent report revealed that MAGI1 mediates tumor metastasis through the c-Myb/miR-520h/MAGI1 signaling pathway in renal cell carcinoma." (PMID 34198584, 2021). "In recent years, studies have shown that MAGI1 can be directly targeted by miR-520-h in renal cell carcinoma (RCC) cells." (PMID 34876130, 2021). "At the same time, MYB promotes the transcriptional activity of miR-520-h by binding to the RCC promoter to regulate MAGI1 expression, and the overexpression or knockout of MAGI1 regulates PETN/MAGI1/β-Catenin and significantly affects the invasion and migration of human renal cell carcinoma cells." (PMID 34876130, 2021).